CRP (C-reactive protein)
Diseases named in the same sentence as CRP in open-access papers (continued):
Sharing a sentence is not in itself a finding about the gene and the disease.
depression (continued). "However, significant differences were observed in insomnia status (P = 0.049), sleep duration (P < 0.001), frailty score (P < 0.001), EA (P < 0.001), hs-CRP (P = 0.023), and depression score (P < 0.001)." (PMID 40662139, 2025). "All remaining associations between biological ages (including all difference or residual scores of epigenetic or brain age) and measures of physical (CRP), cognitive or mental health (cognition, depression) were weak and insignificant (standardized regression betas ranged between − 0.36 and 0.28)." (PMID 40695906, 2025). "Furthermore, individuals with depression often exhibit elevated levels of CRP and TNF in their blood." (PMID 40852367, 2025). "In addition, a cross-sectional study correlated elevated CRP levels in psoriasis patients with depression." (PMID 40563994, 2025). "Depression exhibits close associations with elevated systemic inflammatory cytokines including interleukin-6 (IL-6), IL-1β, tumor necrosis factor-α (TNF-α), and C-reactive protein (CRP)." (PMID 40508038, 2025). "It is worth noting at the outset that CRP may serve as an inflammatory marker useful in the personalized treatment of depression." (PMID 40507778, 2025). "For instance, raised levels of CRP (>3 mg/L) in patients with depression, together with elevated levels of IL-6 and other inflammatory cytokines in blood and cerebrospinal fluid in patients with depression, are indicators of low-grade systemic inflammation." (PMID 38545720, 2025). "However, the relationship between CRP levels and depression in patients with ALS remains underexplored." (PMID 41018179, 2025). "We detected significant reductions in hs‐CRP levels (intervention group: change = −0.56 ± 1.29, p = 0.01; control group: change = −0.81 ± 1.16, p < 0.001) and depression scores (intervention group: change = −1.33 ± 3.66, p = 0.04; control group: change = −1.44 ± 2.83, p = 0.01)." (PMID 40808706, 2025). "In non-genetic analyses, higher CRP was associated with depressive disorder, lower positive/higher negative affect, and worse executive function, attention, and psychomotor speed after adjusting for potential confounders." (PMID 40348744, 2025). "While these changes did not predict overall depression severity improvements, higher post-treatment IL-6 correlated with better affective and cognitive outcomes, while CRP reductions linked to neurovegetative symptom relief." (PMID 40896230, 2025). "The emergence of depressive disorders is predicted by inflammatory indicators such as CRP and IL-6." (PMID 40787495, 2025). "Patients in the moderate and severe classes were more often women, had oral cavity cancer, showed impaired performance, had a history of anxiety and depression disorders, were daily smokers, had higher CRP, and had a flatter cortisol slope compared to the mild class." (PMID 40877705, 2025). "In our study, delirious patients exhibited higher post-injury CRP levels compared to non-delirious patients, and elevated CRP levels were associated with higher anxiety and depression scores in patients." (PMID 39554848, 2024). "Some studies have found an association between depression and elevated hs-CRP levels, while others have not." (PMID 38596631, 2024). "Instead, the associations found in observational studies could be explained by IL-6 and other cytokines acting on both CRP and depression." (PMID 38699297, 2024). "The correlation between hs-CRP and depression lacks clarity." (PMID 38596631, 2024). "Those with high levels of TNF but not IL6 or CRP were associated with a greater presence of depression." (PMID 38175420, 2024). "Serum CRP was significantly associated with average fatigue score on FSS (ρ = 0.48, p = 0.004); this association persisted when controlling for age, sex, disability score, and depression (β = 0.49, 95% CI (0.17, 2.26), p = 0.03)." (PMID 38533609, 2024). "In addition, sleep disorders such as insomnia or poor sleep quality, which are common in patients with depression, can also affect CRP levels." (PMID 38255209, 2024).
depression (continued). "It is unclear what accounts for these mixed findings, but potential factors may include CRP SNP selection, definition and/or measurement of depression, statistical power, and selection bias (see Supplementary Discussion)." (PMID 38699368, 2024). "It is proposed that inflammation is a key for depression, with approximately one-third of adults with depression exhibiting elevated levels of inflammatory cytokines, including C-reactive protein (CRP), tumor necrosis factor α (TNF-α), and interleukin-6 (IL-6)." (PMID 40226688, 2024). "Patients with significant depression have impaired connectivity in the ventral striatum, a critical portion of the brain’s reward system, especially when it comes to the degree of inflammation as shown by CRP levels." (PMID 39273641, 2024). "Furthermore, elevated CRP levels have been noted in patients with schizophrenia, as well as in patients with depression." (PMID 39121088, 2024). "However, emerging studies suggest a tangible link between CRP levels and depression, reinforced by meta-analyses revealing heightened CRP levels during stroke's acute phase as a predictor for increased PSD risk." (PMID 38377025, 2024). "Fluctuations in sex hormone levels could also influence the development of depression by altering immune responses and inflammatory markers like C-reactive protein." (PMID 39957754, 2024). "Inflammation, marked by elevated pro-inflammatory cytokines like IL-6, TNF-α, and C-reactive protein, is a shared mechanism between depression and dementia, contributing to neurodegeneration, hippocampal damage, and disrupted neuroplasticity, leading to cognitive impairments." (PMID 39429291, 2024). "In addition, a meta-analysis of clinical trials has shown that ginseng supplementation can reduce serum CRP/hsCRP levels in patients with elevated serum levels of this inflammatory marker, indicating that possible correlation with depression." (PMID 38012459, 2024). "Furthermore, C-reactive protein (CRP), which tends to be chronically elevated in depression and anxiety, has been shown to interact with the gut microbiome and affect the risks of anxiety and depression." (PMID 38756771, 2024). "Mendelian randomization studies have found that elevated plasma CRP levels did not increase the risk of major depression." (PMID 38596631, 2024). "However, the MR literature of CRP on depression is mixed with some studies reporting CRP to decrease or increase risk for depression." (PMID 38699368, 2024). "In contrast to the lack of association with central inflammation, circulating CRP levels were significantly associated with fatigue severity, even when controlling for age, sex, depression, and mRS as additional confounders." (PMID 38533609, 2024). "Studies have shown that patients with severe mental illnesses often have elevated baseline CRP levels, even without infection, due to the chronic low-grade inflammation associated with psychiatric disorders such as schizophrenia and major depressive disorder." (PMID 39408010, 2024). "Also, a higher CRP level at baseline makes an apparent distinction between patients with RA who will ultimately develop depression." (PMID 38610822, 2024). "One plausible mechanism linking grip strength to depression involves low-grade inflammation, a condition prevalent in approximately one-fourth of individuals with depression, with over half of these individuals exhibiting mild elevations in C-reactive protein levels." (PMID 39444807, 2024). "In this context, hs-CRP may be valuable in predicting and assessing early depression as an especially sensitive acute inflammation marker." (PMID 38596631, 2024). "Second, the surge in serum CRP levels post-stroke could indirectly trigger depression through yet-to-be-unveiled mechanisms." (PMID 38377025, 2024). "Nevertheless, CRP remains an important target for monitoring depression." (PMID 39329797, 2024).
depression (continued). "In addition, longitudinal analyses revealed that depression is a significant predictor of IL-6 and, conversely, inflammatory markers (CRP or IL-6) predict future depression." (PMID 38474387, 2024). "Furthermore, increased C reactive protein, TNF-α, and pro-inflammatory cytokines are associated with depression and T2DM." (PMID 39036053, 2024). "In non-genetic analyses, higher CRP was associated with a depressive disorder, lower positive/higher negative affect, and worse executive function, attention, and psychomotor speed after adjusting for potential confounders." (PMID 39149475, 2024). "Depression with peripheral blood CRP > 3 mg/L is usually considered inflammation-related, and patients with this type of MDD are more likely to show treatment resistance, probably due to inflammatory factors block and destroy the action pathways of antidepressants." (PMID 38698338, 2024). "Indeed, recent meta-analyses have reported higher levels of TNF-α, CRP, and IL-6 levels in adolescents with depressive disorders when compared with control individuals." (PMID 38824135, 2024). "Similarly, a high RA prevalence of 34.9% was observed among subjects with depression and HTG at the medium CRP level, while the prevalence of RA among subjects with depression and HTG alone were 16.3% and 5.6%, respectively." (PMID 38455932, 2023). "CRP level increases in depressive episodes and to a greater degree in manic episodes." (PMID 37340368, 2023). "Higher CSF levels of CRP and MCP-1 were also associated with depression and fatigue." (PMID 36906614, 2023). "Therefore, neuroinflammation has gained increasing attention and is regarded as a key role in depression; IL-6, IFN-α, and C-reactive protein (CRP) have been shown to be linked to depression." (PMID 37630578, 2023). "Depression may be characterized by elevated pro-inflammatory signaling via leptin concentrations through alternate inflammatory pathways distinct to CRP." (PMID 37443383, 2023). "None of these four studies reported that the association between CRP and depression was only significant for participants with HIV and not for those without HIV." (PMID 37693812, 2023). "Notably, elevated serum CRP is positively related to the somatic symptom profile of atypical depression: This “inflammatory phenotype” includes symptoms of fatigue, hypersomnia, leaden paralysis, increased appetite, weight gain, and anhedonia." (PMID 36831896, 2023). "Elevated levels of C-reactive protein were associated with depression and disrupted physical activity, but there were no other significant associations between inflammation and treatment-related symptoms." (PMID 37444517, 2023). "Furthermore, high blood CRP and IL6 levels have been associated with greater depression symptom severity, obsessive compulsive disorder (OCD) anxiety and psychological distress." (PMID 38275640, 2023). "Regarding specific objectives, the analysis of symptoms of depression (BDI-II scale score) given the levels of CRP and IL-6 will be conducted using linear mixed models, adjusted for age, BMI, hemoglobin HbA1C, medication, physical activity, smoking and drinking habits and sex." (PMID 37016319, 2023). "Although the autoregressive, CRP main-effect, depression main-effect, and reciprocal models yielded a good fit to the data across all fit indices, the other three models did not significantly differ from the autoregressive model (△χ2s > 0.00, ps > 0.05, △CFIs<0.01)." (PMID 36860788, 2023). "Future studies focusing on different depression subtypes, abnormally high CRP levels, and a larger number of inflammatory markers may further our knowledge of these complex interactions." (PMID 36712567, 2023). "As with loneliness, other research suggests that the relationship between CRP and depression may be influenced by race/ethnicity and sex, which would be an important avenue for future research." (PMID 37651083, 2023).
depression (continued). "Our findings, however, do not support a major causal role of serum CRP as a determinant of anxiety and depression symptoms and life satisfaction." (PMID 37217205, 2023). "This raises the question of whether serum/plasma CRP is the best discriminant to identify the immune-related phenotypes of depression." (PMID 37264010, 2023). "When treating depression as a binary outcome, serum magnesium was associated with ORs of depression in individuals with CRP levels ≥ 5 mg/L, but not in those with CRP levels < 5 mg/L." (PMID 37049401, 2023). "Indeed, depression was recently characterized as a pro-inflammatory state in a large meta-analysis which found robust elevations of CRP, and proinflammatory cytokines IL-6, IL-3, IL-6, IL-12, IL-18, soluble IL-2 receptor, and TNF-α." (PMID 37614344, 2023). "Here are a few reports addressing the CRP gene in depression and bipolar disorder." (PMID 37181328, 2023). "However, it seems unlikely that serum CRP and serum IL-6 should have major different effects on anxiety and depression symptoms in this group compared with other populations." (PMID 37217205, 2023). "Thus, the mechanism between genetically proxied inflammatory cytokines and depression, similar to that of CRP and schizophrenia, needs further studying." (PMID 37600668, 2023). "Previous studies in depression have found that CRP in serum/plasma is correlated with both CRP in the cerebrospinal fluid (CSF) and CSF pro-inflammatory cytokines, and that blood CRP, IL-6 and neutrophils levels are correlated with dysconnectivity of a brain functional network." (PMID 37264010, 2023). "Correlation analyses between continuous control variables, depression and CRP." (PMID 36860788, 2023). "The best-fit PRSs were used as genetic instruments in the 1-sample mendelian randomization analyses for each exposure (with P value thresholds of 0.05 for endometriosis, >.99 for depression.05 for anxiety, >.99 for anorexia nervosa, and 10−5 for CRP) (eTable 6 in Supplement 1)." (PMID 36652249, 2023). "IL-6 and CRP also increase in patients with anxiety and depression." (PMID 36873198, 2023). "Similarly, the results of a clinical trial study assessing depression, metabolic syndrome, and inflammatory markers showed that increased appetite in depressed patients was positively correlated with CRP and HIF-α." (PMID 37492068, 2023). "In addition, there is a strong link between increased level of the inflammatory markers such as C‐reactive protein (CRP) and depression." (PMID 37537722, 2023). "Furthermore, studies have shown increased CRP levels related to depression, suicidal behavior, GAD, CFS, and cognitive impairment." (PMID 36675440, 2023). "Similarly, higher levels of TNF-α, IL-1, IL-6, and CRP are reported in subjects with increased depression." (PMID 38455932, 2023). "As found in the study, RDW could robustly predict post-ICH depression (AUC: 0.665) compared to CRP (AUC: 0.697) and WBC (AUC: 0.692)." (PMID 37090985, 2023). "In fact, it is unclear from existing studies whether CRP levels directly contribute to the onset and progression of depression." (PMID 36860788, 2023). "Those individuals with higher serum magnesium showed lower ORs of depression in the subgroup with CRP levels ≥ 5 mg/L (0.14 in the crude model, 0.11 in Model 1, 0.11 in Model 2) than in the subgroup with CRP levels ≥ 3 mg/L (0.21 in the crude model, 0.21 in Model 1, 0.23 in Model 2)." (PMID 37049401, 2023). "There is no unifying diagnostic criteria for depression associated with inflammation, however a peripheral C-reactive protein (CRP) level exceeding 3 mg/L is commonly used as a marker of subtyping inflammation." (PMID 37252156, 2023). "To clarify the influence of inflammatory markers and SCFAs on the relationship between gut microbiota and depression, we are considering incorporating additional blood tests for other inflammatory markers, such as C-reactive protein, and tests for intestinal SCFAs into samples from the IHPP." (PMID 37764129, 2023).
depression (continued). "A previous study reported that child maltreatment is associated with comorbid conditions of depression and inflammation (C-reactive protein—CRP) in adults with a history of child maltreatment, but not among those without such experiences." (PMID 37239632, 2023). "The effects of categorical control variables on depression and CRP." (PMID 36860788, 2023). "As such, the different proteins may differentially effect depression giving an overall null result (e.g. CRP has been found to have protective effects on depression)." (PMID 37196932, 2023). "Plausibly, increased CRP and fibrinogen predicted heightened depression components, particularly somatic symptoms, by producing more proinflammatory cytokines from peripheral blood mononuclear cells (e.g. IL-6, tumor necrosis factor-α) (Haroon, Raison, & Miller, 2012)." (PMID 35924730, 2023). "Indeed, previous studies have shown that concentrations of inflammatory markers such as C-reactive protein and interleukin-6 correlate with the scores of depression and anxiety, supporting our findings." (PMID 37138731, 2023). "Furthermore, CRP’s well-known impacts ontreatment response in depression seem to further be explained by the changes ininsulin regulation." (PMID 36377525, 2023). "Prognostically, suboptimal CRP and associated markers (e.g. fibrinogen, HDL, triglycerides, LDL levels) are probably proinflammatory proteins and surrogate lipid markers driving the etiology of depression." (PMID 35924730, 2023). "Further research may investigate whether the mtDNA × CRP interactions provide a mechanistic explanation to the sex difference in the prevalence of anxiety and depression." (PMID 37344456, 2023). "There is a direct association between depression severity and CRP levels in women, whereas CRP levels do not correlate with depressive symptoms in men." (PMID 38132659, 2023). "This analysis could permit to corroborate or discard the previous associations reported between studied psychological variables, including positive affect, depression and anxiety and CRP." (PMID 37241046, 2023). "Previous studies have reported that patients with kidney disease have higher levels of interleukin-6 (IL-6) and C-reactive protein, which are both considered to be related to the severity of depression due to increased production through various pro-inflammatory pathways and decreased clearance." (PMID 37006563, 2023). "Fourth, a measure of increased appetite, which has been identified as a key factor driving the association of depression with BMI and CRP, was not available in ELSA." (PMID 36462595, 2023). "Moreover, several depression-linked genetic variants in pro-inflammatory genes, including in IL1B, TNFA, and CRP, are associated with decreased expression." (PMID 37217515, 2023). "CRP has been found to be elevated in children and adolescents with comorbid asthma and depression." (PMID 38274547, 2023). "This study investigated whether the inflammatory marker, CRP, could prospectively predict symptoms of depression in middle-aged and older adults using a prospective design of community and rural dwellings, accounting for a range of potential confounders." (PMID 36860788, 2023). "Additionally, previous study demonstrated that patients with major depression exhibited a reduction in TNF-αand CRP levels following treatment with antidepressants." (PMID 37587401, 2023). "In addition, a higher risk of depression has been linked to higher levels of Interferon gamma (IFN-γ), Interleukin 2 (IL-2), TNF-α as pro-inflammatory cytokines, and inflammatory markers as C-reactive protein (CRP)." (PMID 37386551, 2023). "A recent Mendelian Randomisation (MR) study suggested that CRP may decrease and IL-6 may increase anxiety and depression symptoms." (PMID 37217205, 2023). "However, the levels of CRP were higher in breast and prostate cancer patients with depression as compared to BC and PC patients, respectively." (PMID 37153524, 2023).